CD200 (CD200 molecule)
Diseases named in the same sentence as CD200 in open-access papers (continued):
Sharing a sentence is not in itself a finding about the gene and the disease.
tumor (continued). "In support of these studies, targeted disruption of CD200 expression in cSCC tumor cells and Ctsk pharmacological inhibition reduced cSCC metastasis in vivo." (PMID 38540350, 2024). "CD200 is a glycoprotein that is expressed in the stromal, epithelial, and tumor cells, though CD200 expression has also been reported on small subsets of T cells, B cells, and dendritic cells." (PMID 38619621, 2024). "The presence of CD200 on the surface of tumor cells directly inhibits the immune system’s attack on the tumor cells and allows cancerous cells to escape detection." (PMID 39795972, 2024). "The difference in the CD200 expression between normal tissues and tumor-invaded tissues is significant and strongly influence the dynamics of the tumor development." (PMID 39795972, 2024). "It is worth noting that IDO1, IDO2, CD44, and CD200 are up-regulated in the FRM high-risk group, all of which are related to the tumor microenvironment." (PMID 38534739, 2024). "The focus of our immunotherapy research has been on combining autologous tumor lysate (ATL) with an ICI for the CD200 immune checkpoint." (PMID 39794971, 2024). "Extensive research has found the critical role of CD200 in the tumor microenvironment through the regulation of the functions of various immune cells." (PMID 39795972, 2024). "The therapies targeting CD200/CD200R block or interrupt immunosuppressive signals mediated by CD200 on tumor cells and augment immune attack against tumors." (PMID 39795972, 2024). "This showed that CD200 plays a part in regulating the invasion of immune cells into the tumor microenvironment and their further activity." (PMID 39795972, 2024). "We discovered that CD200 was overexpressed on immune, stromal, and tumor populations in the pancreatic TME." (PMID 38619621, 2024). "By understanding each patient’s own tumor and immune system interactions, personalized treatment can be accomplished with the use of CD200-targeted strategies." (PMID 39795972, 2024). "Its ligand, CD200, is expressed by T cells, B cells, macrophages, microglia, endothelial cells, neurons, stromal cells, and tumor cells." (PMID 39409893, 2024). "The blockade of CD200, in preclinical models, by anti-CD200 monoclonal antibodies was demonstrated to reduce tumor metastasis and increase cytotoxic antitumor immune cells in lymph nodes." (PMID 39795972, 2024). "As detailed above, a number of in vivo studies have suggested a role for CD200:CD200R interactions in the control of tumor invasion." (PMID 38540350, 2024). "The involvement of lncRNAs, including MIR200CHG, in tumor behavior and resistance is extensive, although their connection to CD200-targeted therapies is still unclear." (PMID 39795972, 2024). "CD200, also known as OX-2, is a cell surface glycoprotein expressed by a wide variety of cells, including tumor cells, endothelial fibroblasts, and immune cells." (PMID 39403603, 2024). "Conjugated with a peptidic inhibitor, CD200 proteins target important pathways to decrease the immune suppression of the tumor and amplify immune activity." (PMID 39795972, 2024). "Regarding treatment, following surgical resection, all dogs received autologous tumor lysate vaccination with our CD200 immune checkpoint inhibitor as intradermal injections." (PMID 39794971, 2024). "CD200 + CD8 + T cells were previously reported to be crucial for effective PD-1/PDL-1 blockade in murine tumor models." (PMID 38619621, 2024). "Their study showed that 23.7% (nine out of 38) of PTLD patients exhibited CD200 positivity and that tumor cells exhibited membrane and cytoplasmic CD200 positivity." (PMID 39224537, 2024). "These myeloid cells are believed to interact directly with tumor cells via the CD200/CD200R interaction, making them susceptible to CD200-mediated inhibition." (PMID 38137547, 2023). "Further supporting this concept, in syngeneic and xenograft murine tumor models, treatment with CD200 neutralizing antibodies restored lymphocyte-mediated anti-tumor responses in vivo." (PMID 36738455, 2023).
tumor (continued). "CD200 binds to its cognate receptor, CD200R, which is highly expressed in the tumor microenvironment (TME) on TAMCs, including tumor-associated macrophages (TAMs), myeloid-derived suppressor cells (MDSCs), and tumor-associated dendritic cells (TADCs)." (PMID 38137547, 2023). "One such proposed property of CD200 is the suppression of natural killer (NK) cell anti-tumor responses via engagement with CD200R on NK cells." (PMID 38137547, 2023). "An underexplored aspect of the role of CD200 in cancer is the identification of tumor-specific mechanisms for the regulation of CD200 expression." (PMID 36738455, 2023). "Using Samalizumab, a recombinant humanized anti-CD200 monoclonal antibody, this study found that CD200/CD200R blockade restored CTL-mediated anti-tumor activity and reduced tumor burden in 14/23 CLL patients, though 16 patients achieved stable disease." (PMID 38137547, 2023). "CD200 regulates tumor immunity by interacting with the inhibitory receptor CD200R within the tumor microenvironment." (PMID 37894750, 2023). "Immunofluorescence staining revealed that CD200 was highly expressed on tumor epithelial cells and on stromal cells within the PDAC TME." (PMID 36756156, 2023). "This reduced the efficacy of anti-PD-L1 treatment in inhibiting tumor growth, indicating that CD200 expression is necessary for effective ICB therapy." (PMID 38137547, 2023). "Studying the impact of CD200 on the tumor microenvironment and its dynamic changes throughout tumor progression will also provide insights into the context-specific roles of CD200 in cancer." (PMID 38137547, 2023). "The research highlighted potential limitations, including variable CD200 expression on tumor cells and differences in tumor microenvironments between subcutaneous and other tumor models." (PMID 38137547, 2023). "Both tumours expressed high levels of MHC-I as well as PD-L1, whereas CD200 expression continued to be restricted to MC38 tumours." (PMID 37082107, 2023). "The investigators demonstrated that CD200 downregulates NK cells’ anti-tumor activity by suppressing their activation, degranulation, and release of both cytokines and chemokines." (PMID 36756156, 2023). "Another inhibitory receptor expressed on NK cells is CD200R which binds to its ligand CD200 expressed on various tumor tissues." (PMID 37228595, 2023). "Herein, we will summarize the current understanding of CD200 expression and function in the tumor microenvironment as well as alternative strategies for potential neutralization of multiple CD200 mechanisms in human cancers." (PMID 36738455, 2023). "By interacting with its inhibitory receptor CD200R, CD200 suppresses immune cell activity within the tumor microenvironment, creating conditions that foster tumor growth." (PMID 36756156, 2023). "It was previously found that tumor vascular endothelial cells in GBM had upregulated levels of CD200 expression." (PMID 36756156, 2023). "This indicates a potential CD200-mediated suppression of T cell metabolism, thus indirectly compromising these immune cells’ cytotoxic functions, ability to maintain tumor immunosurveillance, and maintenance of prolonged anti-tumor/anti-viral responses." (PMID 38137547, 2023). "There has been some work into anti-CD200 targeted therapy and that anti-CD200 can supress tumour cells and restore tumour immune control in an animal model." (PMID 37822353, 2023). "The immune checkpoint role of CD200 on dendritic cells and lymphoid effector cells can regulate the activation of inflammatory immune responses and tumor tolerance." (PMID 37533738, 2023). "Blockade of CD200/CD200R interactions using monoclonal antibodies like Samalizumab and TTI-CD200 has shown promise in restoring anti-tumor immunity, particularly in hematologic malignancies." (PMID 38137547, 2023). "These functions enable CD200+ CTLs to exert their neoantigen-specific cytolytic activities to a higher degree and ultimately induce tumor cell death." (PMID 38137547, 2023).
tumor (continued). "The overexpression of CD200 has also been involved in the pathogenesis of various tumours including renal, colon, testicular head and neck carcinoma." (PMID 37822353, 2023). "Using an E.G7 T cell lymphoma cell line and MC38-OVA epithelium-derived tumor model, co-inoculation with CD200+ CTLs prevented tumor formation in three of four mice and two of four mice, respectively." (PMID 38137547, 2023). "This definitive role for the CD200-CD200R axis in regulating an immunosuppressive tumor microenvironment has garnered increasing interest in CD200 as a candidate target for immune checkpoint inhibition therapy." (PMID 36738455, 2023). "CD200 has also been demonstrated to exert pro-tumor effects through intracellular signaling cascades within tumor cells that operate independently of CD200R." (PMID 38137547, 2023). "This review will explore CD200 and the protein’s expression and role within the tumor microenvironment, blood endothelial cells, and lymph nodes." (PMID 36756156, 2023). "With all things considered, targeting CD200/CD200R has the potential to therapeutically bolster anti-tumor activity within the TME, surrounding blood vessels, and lymph nodes." (PMID 36756156, 2023). "CD200 plays an important role in the regulation of tumor microenvironment and is also an indicator of MRD detection." (PMID 37533738, 2023). "Next, we selected four genes upregulated in fLECs in tumor-draining LNs, namely, Pdpn (podoplanin), Cd200, Bst2 (tetherin, CD317), and Tnc (tenascin), for confirmation on the protein levels." (PMID 35892863, 2022). "Consistent with a hair follicle adult tissue stem cell of origin, 1% to 3% of BCC cells expressed CD200 (OX-2), which demonstrates a 1500-fold tumor-initiating-cell enrichment compared with unsorted cells." (PMID 36074574, 2022). "Conversely, other studies have found that CD200 expression on tumor cells can reduce tumor growth and metastasis and increase the efficacy of T cell therapy." (PMID 35892863, 2022). "CD200 is broadly expressed on endothelial, hematopoietic, and tumor cells and can act as an immune-inhibitory molecule to impair macrophage and DC activation." (PMID 35892863, 2022). "A further 7 days after treatment, larger UWBCC1POS tumors after CD200-blocking antibody treatment demonstrated reduced cellularity (P < 0.05) from increased immune cell infiltrate (P < 0.05) and tumor necrosis (P < 0.05)." (PMID 36074574, 2022). "The development of tumor heterogeneity prevented CD200+ cell detection by immunohistochemistry in the BCC and SCC xenografts." (PMID 36074574, 2022). "Yet for many cancer types CD200 expression is limited to a subset of tumor cells, notably BCC where its expression is restricted to a small cancer stem cell population." (PMID 36074574, 2022). "In contrast, the immune-regulatory molecule CD200 was expressed mainly by fLECs at steady-state, and further induced in tumor-draining LNs." (PMID 35892863, 2022). "UWBCC1POS and UWBCC1NEG cells were grafted into the flank of mice and allowed to establish tumor growth for 4 weeks, when tumors were approximately 10 mm in diameter, and intraperitoneal CD200-blocking antibody was administered daily for 7 days." (PMID 36074574, 2022). "We also characterized the expression of CD200 in both the tumor and stromal compartments of PDAC patients." (PMID 34771664, 2021). "In contrast, the expression of the ligand CD200 was higher in CD4+ T cells in the tumor than in CD4+ T cells from a normal lung (LFC = 3.9, p.adj = 0.0009)." (PMID 33918618, 2021). "The anti-CD200 monoclonal antibody identifies a surface membrane antigen that has recently emerged as a useful tool to better discriminate among neoplasias of mature B lymphocytes." (PMID 34439393, 2021). "On the opposite end of the spectrum, it was observed that CD200–/– mice had reduced carcinogen-induced tumor development." (PMID 34692697, 2021).
tumor (continued). "In the present study, we further showed that the activation of TLR4 by M3G did not affect the levels of other common immune checkpoints, including PD-L2, Gal-9, and CD200 on the tumor cells, but just modulated PD-L1 expression." (PMID 33628591, 2021). "CD200 demonstrated visibly heterogeneous expression patterns in both tumor and stromal cells, as observed in two representative tumor cores." (PMID 34771664, 2021). "In tumor cells, CD200 demonstrated low correlations of expression between different blocks in all positive patients (R2 = 0.16)." (PMID 34771664, 2021). "Expression of CD200 on tumor cells incites the expansion of MDSCs in tumor microenvironment and increases tumor-increased immunosuppression." (PMID 33562512, 2021). "This value demonstrates that across PDAC patients, patients who have high CD200 tumor expression tend to also have high CD200 stromal expression." (PMID 34771664, 2021). "Overall, these results indicate that tumor CD200 interacts with CD200R and limits the secretion of CCL8." (PMID 34692697, 2021). "We observed a predominantly membranous or cytoplasmic CD200 staining pattern in both tumor and stromal cells." (PMID 33804482, 2021). "PD-L1 expression showed weak correlation with CD200 expression when both were measured within the tumor compartment (R2 = 0.28) and moderate correlation when measured within the stromal compartment (R2 = 0.40)." (PMID 33804482, 2021). "Tumor CD200 expression was correlated with significantly decreased tumor infiltration from CD4-positive and CD8-positive T cells and decreased production of IFNγ and TNFα." (PMID 33804482, 2021). "CD200 expression was found to be heterogeneously expressed in the stroma in the majority of patients and in tumor cells in the minority of patients." (PMID 34771664, 2021). "CD200 blockade significantly inhibits tumor growth and diminishes the percentage and number of MDSCs that penetrate in tumor tissue." (PMID 33562512, 2021). "Analysis of tumor immune microenvironment (TIME) revealed that tumors from CD200R–/– or anti-CD200 treated mice had downregulated immune cell contents and reduced TCR clonality compared to tumors from untreated wild type mice." (PMID 34692697, 2021). "In one study on patients with NSCLC, CD200/CD200R1 expression in tumor and stroma was investigated with IHC, and high CD200R1 expression was associated with worse survival." (PMID 33918618, 2021). "PD-L2, Gal-9, and CD200 are other commonly recognized checkpoints that compromise the function of CTLs in the tumor microenvironment." (PMID 33628591, 2021). "The regulatory processes allowing tumor progression are linked to the induction/ production of regulatory molecules by DCs, such as TGF-β, PD-L1, PD-L2 and CD200." (PMID 34847189, 2021). "CD200 is expressed in different cell types and plays an important role in immunosuppression and regulation of anti-tumor activity." (PMID 32157376, 2020). "When the Namalwa tumor cells were engineered to express human CD200 on their surface and simultaneously injected with hPBMCs, CD200 expressed on tumor cells prevented hPBMCs from eradicating the cancer cells." (PMID 33324560, 2020). "In this context, the use of a tumor vaccine consisting of irradiated autologous tumor cells coated with an antibody targeting the CD200 immunoregulatory molecule has shown to be effective in a xenogenic model of CLL." (PMID 33312177, 2020). "CD200 is a protein expressed on the tumor cell surface, and it is able to promote immunosuppression." (PMID 32120774, 2020). "In contrast, CD200 overexpression in CD200 transgenic mice was found to increase tumor-induced IFN-γ and decrease inflammatory cytokine, TNF-α, and IL-6 expression." (PMID 32635224, 2020). "Of the genes queried, CD276 (B7-H3) and CD200 had the highest expression in both the tumor samples and the JN-DSRCT-1 cell line." (PMID 32703985, 2020).
tumor (continued). "Our most important finding was the correlation between metastatic pattern and high expression patterns of CD200 on tumor cells together with CD200R1 expression on stromal cells." (PMID 30800162, 2019). "We showed that tumor-stroma communication through CD200 and its receptor interaction is selected in patients with high risk of relapse." (PMID 30800162, 2019). "For that reason, we assessed the relationship between expression patterns of tumor cell proliferation marker Ki-67 and CD200:CD200R1." (PMID 30800162, 2019). "Independent groups have determined that serum levels of soluble CD200 in cancer patients correlates with tumor burden, which was supported by data in this manuscript." (PMID 30682795, 2019). "The association between CD200 expression and clinical features of HNSCC patients with respect to advanced tumor grade was analyzed using TCGA." (PMID 31627350, 2019). "The results of immunohistochemical analysis showed a strikingly high level of CD200 in tumor cells (p=0.001) and CD200R1 expression in normal mucosal epithelium and stromal cells." (PMID 30800162, 2019). "In AML, high expression of the immunosuppressive glycoprotein CD200 on tumor cells has been shown to directly impair NK cell anti-tumor responses and is associated with downregulated expression of NKp44 and NKp46 receptors on NK cells." (PMID 31474977, 2019). "The positivity of CD200 in SPNs confirms this correlation, since all tumor cells of our SPN cohort had nuclear β-catenin." (PMID 30132130, 2019). "More than that, 87% of metastatic patients had a phenotype of upregulated CD200 in tumor cells accompanied by overexpressed CD200R1 in stromal cells." (PMID 30800162, 2019). "In syngeneic and xenograft murine models, treatment with anti-CD200 antibodies restored lymphocyte mediated anti-tumor responses in vivo." (PMID 31443741, 2019). "In many aspects, the biologic properties of CD200 render it well suited as a biomarker for tumor burden." (PMID 30682795, 2019). "In some neoplasms, CD200-positive tumor cells exhibit cancer stem cell properties, capable of self-renewal and displaying pluripotent potential." (PMID 30132130, 2019). "In vitro and in vivo studies showed that CD200-expressing tumor cells can suppress T-cell responses." (PMID 30800162, 2019). "Secondary endpoints were samalizumab binding to CD200, pharmacodynamic effects on circulating tumor cells and leukocyte subsets, and clinical responses." (PMID 31443741, 2019). "Elevated levels of CD200 are found in multiple types of cancer and many reports suggest that it is responsible for the suppression of anti-tumor immune responses." (PMID 30653571, 2019). "We herein report an intrinsic ‘non-canonical’ intracellular signaling pathway driven by the membrane protein CD200, whereby it exclusively induces ‘pro-tumor’ phenotypes." (PMID 31627350, 2019). "CD200fc treatment on the other hand partly preserved perivascular CD200 expression throughout the tumor growth." (PMID 29721190, 2018). "Similar results using the subcutaneous transplant assay have been obtained with CD200+ cells from BCCs, about 1–2% of the tumor cells." (PMID 29896477, 2018). "Control EMT6 or EMT6siCD200 tumors in WT or CD200-/- mice were resected 15 days after tumor cell injection." (PMID 28234914, 2017). "Silencing CD200 expression in EMT6siCD200 tumor cells also reduced their ability to grow and metastasize in WT animals." (PMID 28234914, 2017). "In contrast to these data, incomplete tumor resistance was seen after surgery/immunotherapy in CD200-/- mice, with metastatic growth in lungs and liver detected by 150 days post surgery." (PMID 28234914, 2017). "In contrast, EMT6siCD200 tumors at that time-point were <0.25cm3 in both WT and CD200-/- mice, implying an important role for tumor CD200 expression in regulation of tumor growth in both strains." (PMID 28234914, 2017).